WDR53 (WD repeat domain 53)
Synonyms: MGC64882; MGC12928
Tractability: Antibody: the Human Protein Atlas places it where antibodies can reach. PROTAC: ubiquitination databases record sites on it.
Gene: Protein-coding gene on chromosome 3 (196,552,228 to 196,569,263, reverse strand). Ensembl gene ENSG00000185798.
Subcellular location (Human Protein Atlas): Cytosol; Plasma membrane
Genetic constraint (gnomAD): Loss-of-function variants: 20 observed, 26.2 expected, observed/expected ratio (o/e) 0.76, 90% interval 0.54 to 1.11. The upper end of that interval is the gene's LOEUF score, 1.11, which puts it in group 4 of 6, group 1 being the genes least tolerant of losing a copy. Missense variants: 368 observed, 437.88 expected, observed/expected ratio (o/e) 0.84, 90% interval 0.77 to 0.92. Synonymous variants: 155 observed, 169.38 expected, observed/expected ratio (o/e) 0.92, 90% interval 0.8 to 1.05.
Homologues: Orthologues: chimpanzee WDR53 (99% identical), macaque WDR53 (98% identical), dog WDR53 (90% identical), pig WDR53 (90% identical), rabbit WDR53 (89% identical), mouse Wdr53 (84% identical), guinea pig WDR53 (82% identical), rat Wdr53 (82% identical), tropical clawed frog wdr53 (54% identical), zebrafish wdr53 (48% identical).
Diseases named in the same sentence as WDR53 in open-access papers:
WDR53 is named in the same sentence as 1 disease in open-access papers, as found by Europe PMC text mining. Sharing a sentence is not in itself a finding about the gene and the disease. The quoted sentences say what the papers report.
osteosarcoma (1 paper, 2022). A usually aggressive malignant bone-forming mesenchymal neoplasm, predominantly affecting adolescents and young adults. "Moreover, the expression of DCAF8 was markedly decreased in osteosarcoma tissues than in adjacent normal tissues, and the expression of UHRF2 and WDR53 was not significant between osteosarcoma and normal tissues." (PMID 36060009, 2022).